SDC3 (syndecan 3)
Diseases named in the same sentence as SDC3 in open-access papers (continued):
Sharing a sentence is not in itself a finding about the gene and the disease.
tumor (20 papers, 2007 to 2026). "SDC3 expression is related to tumor-associated macrophages, cancer, and endothelial cells, and hypoxia in the tumor microenvironment." (PMID 41440381, 2025). "Next, we investigated for any potential association of tumor expression of mRNA or protein for GFRα1, GFRα3 and SDC3 with the clinicopathologic features of MC." (PMID 23351331, 2013). "To confirm a potential cause-effect, we performed experiments with tumor cell lines showing increased expression upon in vitro exposure to 1% oxygen or dimethyloxalylglycine, an inhibitor of prolyl hydroxylases, indicating that Sdc-3 expression is promoted by hypoxia inducible factors (HIFs)." (PMID 33117401, 2020). "Moreover, the strong upregulation of Sdc-3 on tumor versus normal tissue indicates that this molecule could be exploited as a tumor-associated antigen in approaches based on cell therapy or antibody drug conjugates." (PMID 33117401, 2020). "SDC3 expression was largely present within the tumor compared to the stroma, and showed a membranous and cytoplasmic staining pattern." (PMID 41148827, 2025). "While other syndecan family members contribute to the progression of multiple cancers, SDC3’s functional contributions to tumor biology remain largely unexplored." (PMID 41148827, 2025). "SDC3 defective macrophages were found to exhibit distinctive gene expression patterns, resulting in impaired tumor cell phagocytosis and increased tumor cell proliferation." (PMID 41148827, 2025). "SDC3 localized to epithelial and stromal cells in tumor tissue and was also expressed in blood vessels." (PMID 35628603, 2022). "This suggests that Sdc3 expression by both tumor cells and the microenvironment have an impact on tumor progression." (PMID 35628603, 2022). "In non-tumor tissues, Sdc1, Sdc2, Sdc3, Sdc4, and Sdcbp were expressed in all four prostate lobes, with no significant quantitative difference among them." (PMID 34445387, 2021). "The Cancer Genome Atlas program (TCGA) data demonstrated that Sdc-3 expression in the tumor microenvironment positively correlates with a hypoxia gene signature." (PMID 33117401, 2020). "We found a significant positive correlation between the macrophage gene signature and both genes across different tumor types, especially for Sdc-3." (PMID 33117401, 2020). "Expression of Sdc-3 by endothelial cells has been previously reported in the context of inflammatory disease but its potential role on tumor angiogenesis is still largely unexplored." (PMID 33117401, 2020). "The pattern of expression of Sdc-4 in tumor infiltrating cells is similar to that of Sdc-3, with the exception of a higher expression on CAFs." (PMID 33117401, 2020). "Experiments performed with DMOG demonstrated that the inhibition of PHDs directly control the expression of Sdc-3, and we confirmed this finding with a HIF-1α deficient tumor cell line, and by the identification of several HREs on the Sdc-3 promoter." (PMID 33117401, 2020). "Finally, seven prognostic genes-ADH5, FAM162A, HS2ST1, INSR, G6PD, GLCE, and SDC3-were found to have the strongest correlation with tumor metastasis." (PMID 38586328, 2024). "Interestingly, cells of the tumor microenvironment such as macrophages and endothelial cells express Sdc3." (PMID 35628603, 2022). "We can only speculate on the underlying reasons for this finding, which could suggest that SDC3 may play a more important role in tumor progression at the early stages of the disease compared with later stages." (PMID 35628603, 2022). "We also found that TRPM2-AS could sponge miR-138-5p to release SDC3, thereby playing a tumor-promotive role in OvC cells." (PMID 33621194, 2021). "We found a broad upregulation of the expression of Sdc-3 in several tumor types." (PMID 33117401, 2020). "Syndecan-3 is expressed on tumor cells, macrophages, and endothelial cells in the TME." (PMID 33117401, 2020).
tumor (continued). "Since FTE data were available in this database, a comparison of cancer epithelium versus FTE was also included and, apart from the stromal derived candidates VCAN and SDC3, as well as MMP15, all other discovered biomarkers were associated with EOC and increased with tumour progression." (PMID 31336942, 2019). "Indeed, SDC3 expressed by macrophages infiltrating tumor tissue may contribute to tumor cell phagocytosis and decreased tumor cell proliferation, thus exhibiting an antitumoral effect." (PMID 41148827, 2025). "Future research should further elucidate SDC3-related signal transduction pathways in the context of breast cancer and a possible antitumoral effect of SDC3 of the tumor microenvironment, which may contribute to its positive predictive value in transcriptome-based survival analysis." (PMID 41148827, 2025). "Although there are limited reported findings on syndecan-3 in BC, existing evidence has suggested that syndecan-3 is linked to hypoxia-associated and glycolytic gene signatures and interacts with the tissue factor pathway inhibitor (TFPI), affecting tumour-associated coagulation." (PMID 41463344, 2025). "Moreover, SDC3 mediates localization of TFPI—a molecule endowed with tumor suppressor activity —to the surface of endothelial, smooth muscle, and breast cancer cells, which may contribute to an antitumoral effect of SDC3 in the breast cancer microenvironment." (PMID 41148827, 2025). "Double staining techniques, for syndecan-3 and CD31 assessed the expression of syndecan-3 expression in tumor blood vessels." (PMID 37370735, 2023). "Taken together, our results indicate that Sdc-3 expression is hypoxia-sensitive and depends on HIF-1α activity in tumor cells." (PMID 33117401, 2020). "In particular, SDC3 and VCAN could be successfully replicated and were significantly overexpressed in tumour stroma compared to healthy stroma." (PMID 31336942, 2019). "Importantly, NCAN, as a component of extracellular matrix, is reported to bind to HSPGs including glypican-1 and syndecan-3 and FGF2 via its C-terminal domain, which was shown to be essential for tumor sphere formation in our experiments." (PMID 29290949, 2017). "Also, SDC3 is expressed in HCC tissue, especially in tumor stromal vessels, suggesting it may play a fundamental role in HCC tumor angiogenesis." (PMID 33990545, 2021). "In contrast to SDC1 and SDC2, both SDC3 and SDC4 were undetectable in the healthy epithelium, or the tumour stroma, but could be immunolocalized both subcellularly and on defined portions of the cell surface of neoplastic cells, with a particular concentration in focal plaque-like structures." (PMID 25935541, 2015). "Survival outcome in patients whose tumor expressed both ARTN and SDC3 was not significantly different to those patients who were negative for both proteins." (PMID 23351331, 2013).
cancer (19 papers, 2008 to 2025). A tumor composed of atypical neoplastic, often pleomorphic cells that invade other tissues. "In conclusion, we provide the first evidence of an association between TFPIα and the GPI-independent syndecan-3 molecule at cell surfaces, including cancer cells." (PMID 25617766, 2015). "Our findings suggest that SDC3 may influence critical cancer hallmarks associated with breast tumorigenesis and cancer progression." (PMID 41148827, 2025). "SDC3, a member of the syndecan proteoglycan family, is rarely reported, especially in cancer-related research." (PMID 33621194, 2021). "Little is known about the function of Sdc-3 in cancer progression and its influence on the immune response." (PMID 33117401, 2020). "In this study, we have found that expression of Sdc-3 is dysregulated in several cancer types and expressed in cancer cells and macrophages, as a result of limited oxygenation in the TME." (PMID 33117401, 2020). "Here we show that Sdc-3 expression is upregulated on several cancer types, especially in solid tumors that are known to be hypoxic." (PMID 33117401, 2020). "Syndecan-3 expression positively correlated with a macrophage gene signature across several TCGA cancer types." (PMID 33117401, 2020). "Recent studies point to important roles for Sdc-3 in inflammatory disease, but the patterns of expression and significance of Sdc-3 in cancer remains unexplored." (PMID 33117401, 2020). "Apart from cancer cells, endothelial cells and macrophages were identified as Sdc-3 expressing cell populations." (PMID 33117401, 2020). "To further explore this finding in other cancer types, we performed correlations between a macrophage gene signature panel comprised of 92 genes and SDC3 or SDC4 genes based on TCGA database." (PMID 33117401, 2020). "The positive signal for SDC3 mRNA was mainly localized in cytoplasm with infrequent expression in the nuclei of carcinoma cells in MC tissue." (PMID 23351331, 2013). "However, the distinct SDC3 expression patterns in each cancer type and its correlation with cancer progression largely remain unexplored." (PMID 41148827, 2025). "Indeed, genes of the hedgehog pathway, found to be affected by SDC3 knockdown in this study, were also expressed more frequently in cancer stem cells." (PMID 35628603, 2022). "However, the patterns of expression and significance of Sdc-3 in cancer and infiltrating immune cells remains unexplored." (PMID 33117401, 2020). "However, its expression is not restricted to neuronal tissues, and recent studies point to important roles of Sdc-3 in inflammatory disease, regulation of energy balance, cancer, angiogenesis, and viral infections." (PMID 33117401, 2020). "We demonstrated an association between TFPIα and syndecan-3 in vascular cells and in cancer cells, which did not appear to depend on HS GAGs." (PMID 25617766, 2015). "Importantly, Sdc-3 expression correlated with a macrophage gene signature in several cancer types." (PMID 33117401, 2020). "This ability of MDK to promote M2 polarization and macrophage infiltration has been demonstrated in several cancers, with several putative receptors being identified including LRP1, Notch2, and syndecan 3 (SDC3)." (PMID 40429950, 2025). "The prognostic model incorporates genes, such as YY2, PDHA1, SDC3, PPP2CB, and PDK3, all of which have been previously reported to influence cancer prognosis." (PMID 41235100, 2025). "Here we outlined the remarkable features of HSPGs, such as GPC1, GPC4, GPC5, SDC1, SDC2, SDC3 and HSPG2, and some HSPG-related proteins like heparanase and SULF1/2, in cancer diagnosis." (PMID 34249755, 2021). "First, we checked SDC3 and SDC4 gene expression levels on malignant and healthy tissue on several types of cancer on the TCGA database." (PMID 33117401, 2020). "Similar to mRNA expression, GFRα1, GFRα3 and SDC3 proteins were localized in the cytoplasm of epithelial cells of mammary ducts and acini in BBD or carcinoma cells in MC." (PMID 23351331, 2013).
cancer (continued). "There is some evidence that Sdc-3 is expressed in the TME and several cancer cell lines, including bladder cancer, hepatocellular carcinoma, mammary carcinoma, ovarian cancer, pancreatic cancer, prostate carcinoma, renal cell carcinoma, and several glioma cell lines." (PMID 33117401, 2020).
infection (4 papers, 2019 to 2025). The state of being infected such as from the introduction of a foreign agent such as serum, vaccine, antigenic substance or organism. "There are four different human syndecans, SDC1, SDC2, SDC3, and SDC4, which are implicated in the infection of many different viruses." (PMID 40569080, 2025). "Among these genes, SDC3 is a DC-specific proteoglycan that interacts with the HIV-1 envelope glycoprotein gp120, facilitating DC infection and transmission of infection of T cells." (PMID 37097752, 2023).
neurodegenerative disease (4 papers, 2021 to 2025). A disorder of the central nervous system characterized by gradual and progressive loss of neural tissue and neurologic function. "Notably, soluble SDC3 has also been implicated in the internalisation and fibrillation of α-synuclein—an event closely associated with neurodegenerative disease pathogenesis." (PMID 40801591, 2025). "SDC3’s ability to bind and internalize these aggregated forms of Aβ and tau contributes to the spread and accumulation of pathological proteins in neurodegenerative diseases." (PMID 40362276, 2025). "The spread of aggregated proteins, facilitated by SDC3, then affects synaptic communication and plasticity, further contributing to cognitive decline in neurodegenerative diseases." (PMID 40362276, 2025). "This review examines the mechanisms by which syndecans, especially SDC3, contribute to the seeding and spreading of pathological protein aggregates in neurodegenerative diseases." (PMID 40362276, 2025). "In neurodegenerative diseases, altered vesicular trafficking and impaired endocytic pathways, including lysosomal dysfunction, may influence the dynamics and localization of SDC3." (PMID 40362276, 2025).
adenocarcinoma (1 paper, 2021). A common cancer characterized by the presence of malignant glandular cells. "In adenocarcinomas, when positive, SDC3 showed moderate immunostaining throughout the cytoplasm of neoplastic epithelial cells of patients with Gleason 3 tumors and weak cytoplasmic and pericellular immunostaining in Gleason 4–5 tumors." (PMID 34445387, 2021).
SDC3 also shares sentences with these, for which no sentence is quoted: glioblastoma (4 papers); bladder cancer (3); hepatocellular carcinoma (3); cutaneous melanoma (2); amyotrophic lateral sclerosis (1); Anxiety (1); atherosclerosis (1); breast invasive carcinoma (1); diabetes (1); dilated cardiomyopathy (1); gastric adenocarcinoma (1); gynecological tumors (1); hyperandrogenemia (1); hyperglycaemia (1); ischemia (1); liver cancer (1); lung adenocarcinoma (1); metabolic syndrome (1); morbid obesity (1); nervous system diseases (1); non-small cell lung carcinoma (1); resistant hypertension (1); thymoma (1).